STAU1 (staufen double-stranded RNA binding protein 1)
Diseases named in the same sentence as STAU1 in open-access papers (continued):
Sharing a sentence is not in itself a finding about the gene and the disease.
tumor (12 papers, 2016 to 2025). "Mechanistically, STAU1 influences mitochondrial metabolism in ERMS by stabilizing mRNAs encoding components of oxidative phosphorylation (OXPHOS), thereby supporting tumor-cell proliferation." (PMID 40508013, 2025). "Results showed that PREX1, CSE1L and STAU1 were significantly overexpressed in tumor tissues than in normal tissues in both cohorts." (PMID 37749132, 2023). "High Stau1 expression in tumor patients correlates with a better survival prognostic compared to low expression of Stau1." (PMID 35008641, 2021). "In order to determine if the differences between sh0 and the two Stau1-KD groups are dependent on proliferation rate and/or tumoral implantation, we performed a linear regression using the natural logarithm (ln) of tumor volume values." (PMID 35008641, 2021). "In GC, upregulated E2F1 expression, targeting the TINCR/STAU1/CDKN2B signaling axis, was positively associated with poor prognosis due to its association with advanced stage and larger tumor size." (PMID 34532281, 2021). "Strikingly, the results showed significantly larger tumor volume at day 35 for tumors initiated with Stau1-KD cell lines than for the sh0 control cell line (741 ± 88 mm3 and 703 ± 87 for sh1 and sh2, respectively, compared to 312 ± 65 mm3 for sh0)." (PMID 35008641, 2021). "Seven of the nine extracts exhibited higher expression of Stau1 in tumors than in normal tissues whereas Stau1 expression was decreased in tumor samples from two patients (T3 and T8)." (PMID 35008641, 2021). "This suggests that the in vivo context plays a major role in tumor growth and that the tumor microenvironment of stromal origin influences the proliferation of Stau1-KD cells in vivo." (PMID 35008641, 2021). "Targeting STAU1 could disrupt tumor-supportive post-transcriptional networks, offering a novel approach for RMS treatment." (PMID 40508013, 2025). "Similarly, H&E staining and immunohistochemical analysis (Ki67, PREX1, CSE1L and STAU1) also support the synergistic effect of three genes on tumor growth." (PMID 37749132, 2023). "Interestingly, the group within overexpression of three genes PREX1, CSE1L and STAU1 presented a largest tumor volume among all tested groups." (PMID 37749132, 2023). "Our results ultimately indicated that a strategy resulting in the destabilization of binding between SPRY4-IT1 and STAU1, using a specific agent such as a small molecule, could be employed to treat tumor patients harboring metastases." (PMID 34163032, 2021). "In vivo, Stau1 depletion favored tumor progression and metastases development." (PMID 35008641, 2021). "To investigate the potential roles of PREX1, CSE1L and STAU1 in CRC pathogenesis, we first compared the expression of these three genes in tumor and adjacent normal tissues in GEO and our own CRC tissues." (PMID 37749132, 2023). "Similarly, using immunofluorescence analysis on tumor slices, we showed that the amount of THBS1 protein was significantly enhanced in Stau1-KD tumors compared to control tumors." (PMID 35008641, 2021). "In the light of these results, we concluded that Stau1 does not affect proliferation of H460 tumor cells but promotes anti-migratory and anti-invasive properties in H460 tumor cell lines." (PMID 35008641, 2021).
infection (5 papers, 2018 to 2023). The state of being infected such as from the introduction of a foreign agent such as serum, vaccine, antigenic substance or organism. "STAU1 has been reported to play an important role in the infection cycle of multiple RNA viruses, including HIV-1, infectious bursal disease virus (IBDV), influenza A virus, enterovirus 71 (EV-A71), Ebola virus, and hepatitis C virus (HCV)." (PMID 34452292, 2021). "The results showed that N proficiently colocalized with STAU1 in SH-SY-5Y at 36 h post-infection, and the expression level of STAU1 was also proportional to the time of infection." (PMID 34452292, 2021). "The lower level of 5′-UTR of viral RNA was measured at 2 h after EV-A71 5′-UTR RNA transfection infection in the Stau1-knockout cells compared with the normal cells." (PMID 30744035, 2019). "To reveal the functional relevance of Stau1 in the EV-A71 infection cycle, we created Stau1 knockout cells." (PMID 30744035, 2019). "In conclusion, we determined the functional relevance of Stau1 in the EV-A71 infection cycle and herein describe the mechanism of Stau1 participation in viral RNA translation through its interaction with viral RNA." (PMID 30744035, 2019). "The presence of Stau1 has been reported in the infection cycles of a number of RNA viruses, including Hepatitis C virus (HCV), influenza A virus, and HIV-1." (PMID 30744035, 2019). "In this study, we investigated the role of Stau1 in viral translation by using a combination of enterovirus 71 (EV-A71) infection, RNA reporter transfection, and in vitro functional and biochemical assays." (PMID 30744035, 2019). "We performed siRNA-mediated depletion of STAU1 in HuH-7 cells, followed by infection of EBOV-eGFP, and determined the yield of infectious particles secreted into cell supernatants by plaque assay." (PMID 30301857, 2018). "Among the 14 hits, depletion of ILF2, ILF3, heterogeneous nuclear ribonucleoprotein L (HNRNPL), and STAU1 significantly decreased EBOV-eGFP infection for each siRNA used." (PMID 30301857, 2018). "As alphaviruses have been previously identified as prime targets for NMD, but are apparently resistant to its effects, the interaction of the CP protein with STAU1 may represent a means by which the NMD pathway is evaded during infection." (PMID 33673546, 2021). "Meanwhile, we found that STAU1 mRNA levels increased during infection." (PMID 34452292, 2021). "EV-A71 infection was then challenged in the Stau1 knockout and normal RD cells." (PMID 30744035, 2019). "Through analyzing Stau1-knockout cells and viral RNA-Stau1 colocalization studies, we provide evidence that Stau1 is involved in the translation of viral RNA during the EV-A71 infection cycle." (PMID 30744035, 2019). "In summary, these data show that STAU1 promotes efficient infection of HuH-7 cells by EBOV." (PMID 30301857, 2018). "STAU1 was recruited to sites of EBOV RNA synthesis upon infection and enhanced viral RNA synthesis." (PMID 30301857, 2018). "In order to explore the mechanism of STAU1 blocking RABV replication, we collected cell samples after infection with RABV at different time points and performed RT-qPCR to analyze the transcript levels of N protein, G protein and STAU1." (PMID 34452292, 2021). "In our experimental setting, the key factor STAU1 showed three-fold increased expression in infected versus non-infected cells at 3 h post-infection." (PMID 36768954, 2023). "We assessed whether STAU1 expression was affected in SARS-CoV-2 infected Calu3 cells expression and found a peak at 3 h post-infection, thus preceding UPF1 and UPF2 upregulation." (PMID 36768954, 2023).
neurodegenerative disease (4 papers, 2018 to 2025). A disorder of the central nervous system characterized by gradual and progressive loss of neural tissue and neurologic function. "Our data suggest protein dyshomeostasis as a common underlying feature of neurodegenerative diseases and that targeting STAU1 may have broad therapeutic potential." (PMID 30194296, 2018). "The increased abundance of STAU1 in neurodegenerative diseases and its association with dysregulation of RNA processing in SCA2 led us to predict that lowering STAU1 levels might be beneficial." (PMID 30194296, 2018). "We studied the role of STAU1 in the chronic activation of the unfolded protein response (UPR), a common feature among neurodegenerative diseases and often directly associated with neuronal death." (PMID 32415281, 2020). "We previously reported that elevations in STAU1 determine autophagy defects and its knockdown is protective in models of several neurodegenerative diseases." (PMID 32415281, 2020). "The sensitivity of STAU1 to cellular stress prompted us to examine whether this pathway was active in other neurodegenerative disease conditions." (PMID 30194296, 2018). "STAU1 may represent a therapeutic target for certain neurodegenerative diseases." (PMID 30194296, 2018). "A central role for STAU1 in the pathogenesis of a neurodegenerative disease has hitherto not been described and should be examined in other diseases." (PMID 30194296, 2018). "In addition, STAU1 elevation in cultured ALS cells, supports that STAU1 could be a therapeutic target for multiple neurodegenerative diseases." (PMID 30194296, 2018).
metabolic disease (2 papers, 2014 to 2025). A congenital disorder (due to inherited enzyme abnormality) or acquired (due to failure of a metabolically important organ) disorder resulting from an abnormal metabolic process. "In metabolic diseases, particularly hepatic insulin resistance and type 2 diabetes, GIGYF2 functions as an RNA-binding protein that enhances STAU1 mRNA stability." (PMID 40643551, 2025).
myopathy (2 papers, 2021 to 2024). A disease of the muscle in which the muscle fibers do not function properly. "In transgenic mice, sustained expression of STAU1 in post-natal skeletal muscle causes a myopathy phenotype by increasing the expression of phosphatase tensin homolog (PTEN) and by inhibiting phosphoinositide-3-kinase (PI3K)/AKT signaling." (PMID 34616743, 2021). "Further overexpression of STAU1 in a mouse model of DM1 exacerbates the myopathy phenotype through a similar mechanism, suggesting that STAU1 is an atrophy-associated gene with impact on progressive muscle wasting in DM1." (PMID 34616743, 2021).
neurological disease (2 papers, 2020 to 2025). "In order to study functional consequences of STAU1 overabundance caused by ER stress in neurological disease, we examined the response of mouse primary cortical neurons and skin fibroblasts derived from WT, or Stau1−/− mice to thapsigargin." (PMID 32415281, 2020). "STAU1 is pathologically overabundant in multiple neurological disorders and contributes to neurodegeneration by exacerbating autophagy dysfunction, endoplasmic reticulum stress, and RNA-protein condensate accumulation." (PMID 41145462, 2025). "We have identified STAU1 as a modulator of apoptotic signaling during ER stress in multiple models of neurological disease and also in normal cells exposed to pharmacological stressors." (PMID 32415281, 2020). "In all, our study describes a novel connection between the RNA-granule protein STAU1 and ER-stress-induced apoptosis that can be targeted in neurological diseases." (PMID 32415281, 2020).
STAU1 also shares sentences with these, for which no sentence is quoted: Alzheimer disease (2 papers); influenza (2); adenocarcinoma (1); Ataxia (1); colorectal adenocarcinoma (1); Ebola (1); esophageal cancer (1); esophageal squamous cell carcinoma (1); Insulin resistance (1); lung adenocarcinoma (1); ovarian carcinoma (1); psoriasis (1).